FASN (fatty acid synthase)
Diseases named in the same sentence as FASN in open-access papers (continued):
Sharing a sentence is not in itself a finding about the gene and the disease.
tumor (continued). "Lipogenic enzymes, such as lipoprotein lipase (LPL) and fatty acid synthase (FAS), are significantly reduced in the adipose tissue adjacent to the tumor, validating the tumor-supporting role of WAT in CAC." (PMID 32117967, 2020). "FASN inhibition attenuates cisplatin-induced apoptosis in receptor positive breast cancer cells, while enhancing cisplatin-induced apoptosis in TNBC tumor cells." (PMID 32296646, 2020). "It seems like FASN is needed for the growth and maintenance of LECs, and FASN inhibitor reduces LEC migration and tumor lymph metastasis." (PMID 33330490, 2020). "We found that the mRNA expression levels of FABP5, FASN, HSL, TWIST1, VEGF-C, and MMP9 were significantly higher in tumours of the bevacizumab group than those of the control group." (PMID 32550890, 2020). "Bergapten inhibits liver carcinogenesis (HepG2) by activating LXRs, inhibiting PI3K/Akt that reduced SREBP-1, fatty acid synthase (FASN), stearoyl-CoA desaturase-1 (SCD1), thereby preventing fatty acid synthesis and tumor growth." (PMID 32781533, 2020). "Fatty Acid Synthase (FASN), a key enzyme of de novo lipogenesis, is significantly upregulated in CRC and promotes tumor growth and metastasis." (PMID 32850342, 2020). "FASN is found upregulated in prostate and breast cancer, and ACLY has been shown to support tumor formation and transformation." (PMID 33194695, 2020). "In this regard, SREBP proteins, which are master regulators of lipid metabolism, together with FASN and SCD have been found to be upregulated in several neoplasias." (PMID 33212825, 2020). "A previous report suggests that the activation of AMPK through phosphorylation inhibits ACC, FASN, SREBP1, and other lipogenesis enzymes, which is the distinctive feature of most of the tumor cells." (PMID 32258129, 2020). "GLS inhibition remarkably increases tumor free survival but upregulates compensatory mechanisms such as transamidases, HK2, FASN, and serine/glycine synthesis." (PMID 33081387, 2020). "In a separate study, artificial amplification of HER2 cDNA in a non-tumor breast epithelial cell line, HB4a, forced the upregulation of lipogenic fatty acid translocase (CD36), fatty acid-binding protein 4 (FABP4) and FASN expression." (PMID 32872164, 2020). "The inhibition of metabolic enzymes such as ALDOA, GAPDH or FASN can prevent or revert EMT in cell models, as can the neutralization of acidic tumor environments." (PMID 31277295, 2019). "In conclusion, FASN is involved in the molecular pathogenesis of HCC, where it plays a pivotal role both in tumor onset and progression." (PMID 31921669, 2019). "To confirm that DNFA enzyme inhibition is the crucial driver for reduced cell viability, we then used small molecule inhibitors of FASN and SCD enzymes, which reportedly decreased tumor growth in preclinical studies." (PMID 31316083, 2019). "In this regard, SREBP proteins, which are master regulators of lipid metabolism, together with FASN and SCD have been found to be upregulated in several neoplasia." (PMID 30913248, 2019). "The results show that inhibition of FASN blocked xenograft tumor growth of NSCLC in vivo, suggesting that FASN contributes to the malignant biological behavior of NSCLC." (PMID 31122252, 2019). "The results indicated that RA-XII strongly inhibited tumor growth and lipogenesis (triglycerides and lipid droplets) in HepG2 cells, and the expression of key factors involved in lipogenesis (SREBP, SCD, FASN) was also obviously downregulated." (PMID 31083642, 2019). "Taken together, all these results suggested that FASN increased the activity of p-ERK1/2/Bcl-xL, and FASN/p-ERK1/2/Bcl-xL pathway played vital roles in tumor and anoikis resistant." (PMID 30931932, 2019). "Mir-195 has been shown to target Bcl-2, inducing apoptosis, and target FASN, HMGCR, ACACA and CYP27B1 in hormone-receptor positive breast cancer cell lines, suppressing tumour growth, EMT, invasion and metastasis." (PMID 31077182, 2019).
tumor (continued). "FASN inhibitors, such as cerulenin, C75, orlistat and epigallocatechin gallate (EGCG), demonstrated anti-tumor activity, leading to toxic accumulation of the malonyl-CoA intermediate, reduction of membranes synthesis and phospholipid function." (PMID 29805774, 2018). "Inhibition of FASN with Orlistat induces EGFR ubiquitination and abrogates EGFR mutant signaling, and reduces tumor growths both in culture systems and in vivo." (PMID 29449326, 2018). "The inhibition of ACC and FASN by TOFA and C75 respectively differentially promoted opposing effects on the production of secretory factors post slippage and consequent tumour-promoting effects." (PMID 30510774, 2018). "The present study revealed the potential role of PHD-2 activators in curtailing the growth of tumor cells by down-regulating the level of HIF-1α and FASN." (PMID 35541235, 2018). "To evaluate the correlation between FASN expression, activation of major oncogenic pathways, and tumor response in vivo, we analyzed the levels of FASN, pAkt, pAMPK, pErk1/2, and TIP47 in tumor tissues from G0 PDX models." (PMID 29872506, 2018). "To investigate the effect of TVB-3664 on tumor metabolism in PDX tumors, we performed untargeted metabolomics on tissue samples from Pt 2449PT, Pt 2402, and Pt 2614, which responded to FASN inhibition." (PMID 29872506, 2018). "Besides the Warburg effect, tumour cells also undergo lipid remodelling mostly characterised by aberrant de novo lipogenesis, cholesterogenesis due to oncogenic-driven lipogenic enzyme overexpression (e.g., fatty-acid synthase (FASN), 3-hydroxy-3-methylglutaryl-CoA reductase (HMGCR))." (PMID 29358673, 2018). "Pharmacological inhibition of FASN with Orlistat triggered cell death in TKI‐resistant cells in culture and reduced tumor burden in both xenografts and transgenic mouse models." (PMID 29449326, 2018). "In contrast, HUH7 cells showed a higher expression of 98 metabolic targets upregulated in tumours (e.g. HK2, PKM, PSPH, GLUL, ASNS, and fatty acid synthesis enzymes ACLY, FASN)." (PMID 30176945, 2018). "A phase I clinical trial of a first-in-class FASN inhibitor, TVB-2640, in patients with solid tumors (ClinicalTrials.gov identifier NCT02223247) shows preliminary anti-tumor activity." (PMID 28654693, 2017). "Lipogenic enzymes, such as acetyl CoA carboxylase (ACC), fatty acid synthase (FASN), ATC citrate lyase (ACLY), are increased in most tumours." (PMID 28752333, 2017). "Serum FASN levels were significantly lower in the HFD group (P=0.026) and correlated inversely with tumour volume (P=0.022)." (PMID 26878389, 2016). "In this study, intracellular FASN expression was higher and P-AMPK expression lower in xenograft tumours of the HFD group than the LFD group." (PMID 26878389, 2016). "FASN and SREBP-1 mRNA expression was 1.8-fold and 2.1-fold higher in xenograft tumours of the HFD group compared with the LFD group, respectively (n=12 per group, P<0.05)." (PMID 26878389, 2016). "In the mice models of the four tumors, consistent with the decline of ACLY, evident lower levels of FASN and HMGCR expression were revealed by IHC staining after the anti-tumor treatment of miR-22." (PMID 27317765, 2016). "Regarding mTOR and FASN inhibition in vivo, EGCG (30 mg/kg for 3d/w) reduced tumor growth in the HER2-PDX model after 21 days of treatment." (PMID 26107737, 2015). "While the levels of FASN mRNA remained unaltered, KLK5-expressing cells exhibited significantly lower rates of free fatty acid (FFA) biosynthesis, which may be linked to suppressed malignancy since it is well-established that decreased FFA is associated with reduced aggressiveness of tumor cells." (PMID 24158494, 2014). "FASN inhibition decreases HER2 expression by up-regulating PEA3, a HER2 transcriptional inhibitor, and by changing the lipid composition and function of tumor cell membranes, thereby altering the cellular localization of HER2." (PMID 24866893, 2014).
tumor (continued). "In addition, how FASN inhibition affects tumor progression remains unclear." (PMID 23741342, 2013). "Orlistat, an inhibitor of fatty acid synthase (FASN), acts as an antitumor agent by blocking de novo fatty acid synthesis of tumor cells." (PMID 24349275, 2013). "Furthermore, we discovered that FASN inhibition suppressed cell proliferation as well as cell adhesion, migration, and invasion and FASN inhibition led to suppression of genes involved in production of arachidonic acid and androgen hormones, both of which promote tumor progression." (PMID 23741342, 2013). "However, how inhibition of FASN suppresses tumor growth remains unclear." (PMID 18523653, 2008). "Others genes in this cluster were targets of estrogen action (e.g. T-type calcium channel subunit; CACNA1G), capable of binding estrogen receptor alpha (FASN, SNCG), or involved in tumor suppression (PRKCD, RASL11A)." (PMID 18941504, 2008). "Univariate analyses revealed a significant difference between tumour and benign hyperplastic tissue for immunohistochemical staining results of FASN (P<0.001), MYC (P<0.001), and PP1α (P=0.020), indicating a role of these proteins in tumour initiation." (PMID 17146477, 2007). "Targeting FGF19 holds therapeutic potential for modulating tumor metabolism by inhibiting the FGFR4-ERK pathway, thereby reducing the expression of key fatty acid synthesis enzymes, such as FASN and ACC, and ultimately disrupting the metabolic support for tumor proliferation." (PMID 41328353, 2026). "In tumor cells, it has been demonstrated that FGF19 can activate downstream signaling pathways, including the FGFR4-ERK pathway, to promote the expression of key enzymes involved in fatty acid synthesis, such as FASN and ACC." (PMID 41328353, 2026). "Although intervention strategies targeting lipid metabolism (such as the fatty acid synthase inhibitor TVB-2640) have shown potential in clinical trials, their efficacy is limited by tumor heterogeneity, metabolic pathway redundancy, and the complexity of host-microbiome interactions." (PMID 40718481, 2025). "Notably, curcumin treatment suppressed the expression of lipid and polyamine biosynthetic enzymes (e.g., FASN, SCD, GLS), indicating a broad reconfiguration of tumor metabolic networks." (PMID 40557160, 2025). "In HCC, key enzymes and transporters involved in de novo lipogenesis, fatty acid uptake, and cholesterol synthesis, such as FASN, SCD1, SREBPs, and fatty acid transport proteins, are frequently dysregulated in tumour tissues, contributing to tumour growth, immune evasion and therapy resistance." (PMID 41154605, 2025). "In addition, IHC analysis of tumor sections revealed a dose-dependent reduction in the expression of SCD1, β-catenin, GPX4, xCT, FASN, and ACC1." (PMID 40070686, 2025). "For instance, studies have shown that the expression of FASN is upregulated in CRC, promoting fatty acid synthesis to provide tumor cells with essential raw materials for biomembrane synthesis and energy, thereby supporting tumor growth and metastasis." (PMID 41031059, 2025). "Tumor cells fulfill their requirements for fatty acids through two primary mechanisms: de novo synthesis via the enzymatic actions of acetyl-CoA carboxylase (ACC) and fatty acid synthase (FASN), as well as the uptake of lipids from the TME." (PMID 40765564, 2025). "Studies have shown that acetate activates FASN gene transcription by increasing the acetylation levels of H3K9, H3K27 and H3K56 in the FASN gene promoter region, thereby enhancing de novo lipid synthesis and tumour growth." (PMID 39778006, 2025). "Additionally, we found that bufalin modulates the SREBP1/FASN pathway via the PI3K/AKT signaling pathways, which is a major regulator of cellular metabolism and tumor progression." (PMID 40942159, 2025).
tumor (continued). "The differential expression of ATP citrate lyase (ACLY), acetyl-CoA carboxylase alpha (ACACA), fatty acid synthase (FASN), SCD, and SREBF1 was further validated via RT‒qPCR subsequent to magnetic-based cell sorting of co-cultured H2228 and H3122 tumor spheroids." (PMID 40524253, 2025). "Additionally, fatty acid synthesis inhibitors like the FASN inhibitor TVB-2640 and glutathione synthesis inhibitors like BSO can reduce tumor reliance on lipids and antioxidants, improving immunotherapy efficacy." (PMID 41020873, 2025). "Molecular docking analysis confirmed that API binds strongly to CDK1, and further experiments demonstrated that API suppresses NiNP-induced tumor growth both in laboratory cell models and in living organisms, while also blocking the activity of the CDK1/STAT3/FASN axis." (PMID 41226659, 2025). "Cisplatin can augment anti-tumor immune responses in combination with immune checkpoint blockers (such as PD-1/PD-L1 or CTLA4 inhibitors), lipid metabolism disruptors (like FASN inhibitors and SCD inhibitors) and nanoparticles (NPs), resulting in better outcomes." (PMID 39757995, 2025). "In contrast, resveratrol, a well-studied polyphenol, mainly targets lipid metabolism by inhibiting FASN and SREBP1, activating the SIRT1–AMPK axis, and altering sphingolipid and cholesterol metabolism, thereby inducing metabolic stress and apoptosis in tumor cells." (PMID 41350297, 2025). "Mechanistic studies suggest that FASN may modulate the AMPK/mTOR and Wnt signaling pathways, contributing to tumour progression, cell proliferation, invasion, and metastasis." (PMID 41154605, 2025). "The transportation of acetate into the cell via MCT1, followed by its translocation into the nucleus, resulted in the activation of oncogenes by enhancing the acetylation of histone H3K27 in the promoter region of the FASN and ACACA genes, ultimately promoting tumor progression." (PMID 40612939, 2025). "Another enzyme, FASN, was found to be upregulated in RCC and stimulated tumor progression." (PMID 41041304, 2025). "Fatty acid synthase (FASN) is a rate-limiting enzyme in FA synthesis, while stearoyl-CoA desaturase-1 (SCD1) converts saturated fatty acids to monounsaturated fatty acids (MUFAs), promoting membrane fluidity and tumour survival." (PMID 41154605, 2025). "Collectively, these results indicate that FASN is highly expressed in colorectal CSCs and is crucial for maintaining CSC characteristics, promoting spheroid formation, in vivo tumor growth, and preserving the CD133+CD44+ CSC population, thus contributing to CRC progression." (PMID 40901481, 2025). "The first-generation FASN inhibitors include C75, orlistat, epigallocatechin gallate (EGCG), and cerulenin, which were initially found to significantly reduce the growth of tumor xenografts, induce cell cycle arrest, and suppress the transcription of oncogenes." (PMID 41421797, 2025). "It is noteworthy that the long non-coding RNA LINC01410 binds to miR-532-5p through a molecular sponge mechanism, thereby relieving its inhibition of FASN, ultimately accelerating LD accumulation and fatty acid metabolic reprogramming, and promoting EMT, invasion, and LNM of tumor cells." (PMID 41472748, 2025). "Notably, the inhibition of fatty acid synthase (FASN), a key enzyme in de novo lipogenesis, has been shown to trigger endoplasmic reticulum (ER) stress in tumor cells." (PMID 40830338, 2025). "By interacting with FASN and USP15, PUMA drives metabolic reprogramming and tumor growth." (PMID 40533456, 2025). "In metabolic targeted therapy, targeting key metabolic enzymes (such as FASN, SCD1, and ACC) and lipid and glucose metabolic pathways can inhibit tumor growth and be combined with immune checkpoint inhibitors and targeted therapy to form personalized treatment plans." (PMID 41281744, 2025).
tumor (continued). "RCCD has a high degree of selectivity of lipid metabolism pathway, 4-Methylumbelliferone (4-MU) was the key active compound with strong binding activity to the core target fatty acid synthase (FAS), and 4-MU down-regulated the expression of FASN in tumor tissues and induced apoptosis in HCC cells." (PMID 40839202, 2025). "Additionally, FASN inhibitors promote the infiltration and activation of CD8+ T cells by upregulating the expression of MHC-I, thereby enhancing the efficacy of tumor immunotherapy." (PMID 40161377, 2025). "Spatial co-localization of polyamines, fatty acids, and key metabolic genes such as FASN and GLS suggested coordinated metabolic reprogramming that may drive tumor progression and immune modulation." (PMID 40557160, 2025). "Tumor cells exhibit characteristic changes in the expression levels and functional dynamics of enzymes critical for lipid metabolism, including acetyl-CoA carboxylase 1 (ACC1), ATP citrate lyase (ACLY) and fatty acid synthase (FASN)." (PMID 41169354, 2025). "We observed a marked increase in apoptosis in BLCA cells following knockdown of FASN or RUNX2, indicating that both genes may promote tumor growth by conferring anti-apoptotic advantages." (PMID 40703521, 2025). "Notably, the expression levels of SREBF1, FASN and SCD1 were significantly decreased in the tumor tissues of iBRD1 and simvastatin treated animals." (PMID 39962068, 2025). "Of the top 20 differentially expressed proteins identified in tumour samples, four (MDH2, FASN, EPCAM, and HSD17B10) are targetable by FDA-approved drugs, whereas two (AMACR and GLYATL1) are potentially targetable and are of potential interest for future research." (PMID 38052461, 2024). "Hematoxylin and eosin (H&E) staining identified an increase in tumor cells in the VCP-overexpressing group, while the immunohistochemical (IHC) analysis showed that in the VCP gene activation group, the expression of FASN, VCP, and USP2 in tumor cells was relatively increased." (PMID 39489738, 2024). "Moreover, FASN expression significantly increases with advanced clinicopathological tumor stage, increased Gleason score, and poor DFS, further indicating that FASN plays a vital role in PCa tumorigenesis and progression." (PMID 39309439, 2024). "The lipase inhibitor orlistat (ORL) prevents the fatty acid synthase (FAS) enzyme from activating its thioesterase domain, which is especially upregulated in many tumor cells, and its inhibition has been shown to suppress tumor growth and metastasis." (PMID 38256929, 2024). "In addition, we further investigated the effects of BMS‐303141 on the expressions of lipid synthesis‐related proteins including SREBF1, MOGAT2, FASN, ACC1, ACS and ACLY in ESCC cells and xenografted tumour tissues by Western blot." (PMID 38426936, 2024). "In addition, both in our IDH1 MT primary tumor cell lines and murine model, VPA inhibited transcription of FASN; hence we focused our attention on FASN." (PMID 39149696, 2024). "Furthermore, in the subcutaneous tumour xenograft model, the expression of USP14 and FASN were increased, while the protein levels of GPX4 were decreased in the group with GSTM3 overexpression." (PMID 38228715, 2024). "In summary, we conclude that in both the IDH1 MT human primary tumor cell lines and in the murine model VPA inhibits growth at least partially via inhibition of the mTOR pathway and that the mTOR pathway is involved in downregulation of FASN." (PMID 39149696, 2024). "Upon manipulating the expression of pathway-associated genes in tumor cells and co-cultivating them with CD8+ T cells, we observed that downregulating PITPNC1 and FASN led to an increased proportion of IFN-γ+ CD8+ T cells, along with heightened cytotoxic effects against tumor cells." (PMID 38291470, 2024). "Combining that only a part of FASN level was recused after C2B domain deletion, we therefore speculated that cytoplasmic TC2N also exerts a tumor-suppressive function in BC." (PMID 38167440, 2024).